PPCDC (phosphopantothenoylcysteine decarboxylase)
Description:
Catalyzes the decarboxylation of the cysteine moiety of 4-phosphopantothenoylcysteine to form 4'-phosphopantotheine and this reaction forms part of the biosynthesis of coenzyme A.
Synonyms: PPC-DC; COAC; MDS018; FLJ14585
Tractability: Small molecule: a structure with a bound ligand is known. PROTAC: ubiquitination databases record sites on it; its protein half-life has been measured.
Safety:
Unwanted effects reported when the protein is acted on. In parentheses: how it was acted on, where the effect was seen, and who reports it.
resume menses following chemotherapy (source: ClinPGx)
Gene: Protein-coding gene on chromosome 15 (75,023,586 to 75,117,462, forward strand). Ensembl gene ENSG00000138621.
Subcellular location (Human Protein Atlas): Cytosol
Pathways (Reactome):
Metabolism: Coenzyme A biosynthesis
Gene Ontology:
Molecular function: FMN binding; identical protein binding; phosphopantothenoylcysteine decarboxylase activity; protein binding; catalytic activity
Biological process: coenzyme A biosynthetic process
Cellular component: phosphopantothenoylcysteine decarboxylase complex; cytosol
Genetic constraint (gnomAD): Loss-of-function variants: 19 observed, 21.13 expected, observed/expected ratio (o/e) 0.9, 90% interval 0.63 to 1.32. The upper end of that interval is the gene's LOEUF score, 1.32, which puts it in group 5 of 6, group 1 being the genes least tolerant of losing a copy. Missense variants: 243 observed, 277.03 expected, observed/expected ratio (o/e) 0.88, 90% interval 0.79 to 0.98. Synonymous variants: 88 observed, 105.66 expected, observed/expected ratio (o/e) 0.83, 90% interval 0.7 to 0.99.
Homologues: Orthologues: chimpanzee PPCDC (99% identical), dog PPCDC (90% identical), pig PPCDC (90% identical), rat Ppcdc (88% identical), mouse Ppcdc (87% identical), guinea pig PPCDC (86% identical), tropical clawed frog ppcdc (70% identical), zebrafish ppcdc (67% identical), Drosophila melanogaster Ppcdc (49% identical), Caenorhabditis elegans F25H9.6 (46% identical).
Diseases named in the same sentence as PPCDC in open-access papers:
PPCDC is named in the same sentence as 6 diseases in open-access papers, as found by Europe PMC text mining. Sharing a sentence is not in itself a finding about the gene and the disease. The quoted sentences say what the papers report.
atherosclerosis (1 paper, 2022). A disease characterized by the build-up of fatty material and calcium deposition in the arterial wall resulting in partial or complete occlusion of the arterial lumen. "Another large study evaluating 12 SNPs in RA patients, identified novel associations between subclinical atherosclerosis and variants in SLC17A2 (rs17526722), PPCDC (rs1867148), COL4A1 (rs496916) and SLCA13 (rs515291) genes, that may constitute new candidate risk loci for CVD in RA89." (PMID 35680906, 2022).
COVID-19 (1 paper, 2021). A disease caused by infection with severe acute respiratory syndrome coronavirus 2. "COVID-19 patients were genotyped for variants in DHCR7/NADSYN1, GC, CYP2R1, VDR, PPCDC and DMGDH genes." (PMID 34150833, 2021). "Therefore, we evaluated genetic determinants of vitamin D (DHCR7/NADSYN1 rs12785878, GC rs2282679, CYP2R1 rs10741657, VDR rs2228570), zinc (PPCDC rs2120019) and selenium (DMGDH rs17823744) as risk factors for severe forms of COVID-19." (PMID 34150833, 2021).
cancer (1 paper, 2016). A tumor composed of atypical neoplastic, often pleomorphic cells that invade other tissues. "An additional three reactions, PNTK, PPCDC and PPNCL3 are part of coenzyme-A synthesis pathways, a pathway also implicated as significantly excluded from cancer models during the clustering analysis." (PMID 26942765, 2016).
PPCDC also shares sentences with these, for which no sentence is quoted: brain disorder (1 paper); malaria (1); tumor (1).